OTOS (otospiralin)
Description:
May be essential for the survival of the neurosensory epithelium of the inner ear.
Synonyms: OTOSP
Tractability: Antibody: UniProt places it where antibodies can reach, with high confidence; UniProt predicts a signal peptide or a membrane-spanning region; its Gene Ontology location is reachable by antibodies, with medium confidence.
Safety:
Unwanted effects reported when the protein is acted on. In parentheses: how it was acted on, where the effect was seen, and who reports it.
ototoxicity (source: ClinPGx)
Gene: Protein-coding gene on chromosome 2 (240,139,026 to 240,144,562, reverse strand). Ensembl gene ENSG00000178602.
Subcellular location: Secreted
Gene Ontology:
Molecular function: protein binding
Biological process: sensory perception of sound
Cellular component: extracellular region
Genetic constraint (gnomAD): Loss-of-function variants: 14 observed, 12.82 expected, observed/expected ratio (o/e) 1.09, 90% interval 0.72 to 1.68. The upper end of that interval is the gene's LOEUF score, 1.68, which puts it in group 6 of 6, group 1 being the genes least tolerant of losing a copy. Missense variants: 141 observed, 108.99 expected, observed/expected ratio (o/e) 1.29, 90% interval 1.13 to 1.49. Synonymous variants: 49 observed, 45.6 expected, observed/expected ratio (o/e) 1.07, 90% interval 0.85 to 1.36.
Homologues: Orthologues: chimpanzee OTOS (100% identical), macaque OTOS (98% identical), dog OTOS (87% identical), pig OTOS (81% identical), mouse Otos (80% identical), rat Otos (80% identical), guinea pig OTOS (79% identical), tropical clawed frog otos (53% identical), zebrafish otos (47% identical).
Diseases named in the same sentence as OTOS in open-access papers:
OTOS is named in the same sentence as 4 diseases in open-access papers, as found by Europe PMC text mining. Sharing a sentence is not in itself a finding about the gene and the disease. The quoted sentences say what the papers report.
deafness (2 papers, 2023 to 2024). An inherited or acquired condition characterized by the complete loss of the ability to hear from one or both ears. "Another notable one is OTOS which is highly expressed in the fibrocytes of the inner ear and the downregulation of this gene can cause irreversible deafness with the severe degeneration of hair cells." (PMID 38672325, 2024). "Thiopurine methyltransferase (TPMT), glutathione-S-transferase pi (GSTP1), cation transporters solute carrier family 22 member 2 (SLC22A2), and numerous deafness-related genes (otospiralin OTOS) have been observed to be associated with cisplatin ototoxicity in some genetics studies." (PMID 37323582, 2023).
OTOS also shares sentences with these, for which no sentence is quoted: Tinnitus (2 papers); hearing loss (1); thyroid tumor (1).